CD4 (CD4 molecule)
Diseases named in the same sentence as CD4 in open-access papers (continued):
Sharing a sentence is not in itself a finding about the gene and the disease.
lymphadenitis (9 papers, 2005 to 2025). Acute or chronic inflammation of one or more lymph nodes. "For paradoxical IRIS both baseline elevated HIV RNA and CD4 depletion were significantly related as already noted for BCG IRIS adenitis in the CHER trial." (PMID 31260455, 2019). "The patient had a baseline CD4 count of 70 cells × 106/L and presented with fever and lymphadenitis within 1 month of starting combination ART." (PMID 24471994, 2014). "One patient had a CD4 cell count of 3/mm3, while the other had a CD4 count of 382/mm3; both presented with lymphadenitis." (PMID 17937815, 2007). "In this line, a previous study associated pDC redistribution and clustering with a worse HIV prognosis, specifically, with lower CD4+ T cell counts and advanced HIV‐lymphadenitis stage." (PMID 40949488, 2025). "In a subset of infants with CD4 < 25% beginning early ART, the frequency of BCG IRIS adenitis was similar to the deferred arm." (PMID 31260455, 2019). "In the CHER trial we reported BCG IRIS adenitis as less common in infants with high CD4 percentages commencing early ART rather than deferred until CD4 depletion triggered ART initiation." (PMID 31260455, 2019). "Patient 4 was admitted with localised MAC associated lymphadenitis of the neck and lacked in vitro proliferative responses to PPD and other recall antigens despite a CD4 T-cell count of 280 cells/l μblood." (PMID 16181494, 2005).
macrophage activation syndrome (9 papers, 2019 to 2026). A complication of rheumatic disease that is caused by excessive activation and uncontrolled proliferation of T lymphocytes and well-differentiated macrophages. "For example, severe COVID-19 patients display macrophage overreaction (also known as macrophage activation syndrome (MAS)) and lymphopenias of effective lymphocytes, including neutrophils, CD4 T cells, and natural killer (NK) cells." (PMID 33322160, 2020). "Patients with severe respiratory failure (SRF) may also show macrophage activation syndrome (MAS) with a prominent reduction in natural killer cells, CD19 lymphocytes, and CD4 lymphocytes." (PMID 35505345, 2022).
metastasis (9 papers, 2021 to 2025). The spread or migration of cancer cells from one part of the body (where they first appeared) to another. "In addition, it was also discovered that the CD4+CXCR5+Tfh cell ratio in the metastasis group also increased significantly." (PMID 35494526, 2022). "The univariate analysis indicated that tumor diameter, degree of tumor differentiation, TNM stage, depth of tumor invasion, lymph node metastasis, and the expression levels of PD-1, PD-L1, FOXP3, CD25, CD4, and CD8 were factors significantly influencing EC prognosis (P < 0.05)." (PMID 40587482, 2025). "Based on the factors selected by the multivariable Cox regression analysis, including tumor diameter, tumor differentiation degree, tumor invasion depth, lymph node metastasis, PD-1, PD-L1, FOXP3, CD25, CD4, and CD8 as independent variables, a nomogram was constructed." (PMID 40587482, 2025).
microsporidiosis (9 papers, 2011 to 2022). A fungal infection caused by Microsporidia. "Nevertheless, intraocular microsporidiosis due to E. cuniculi in a human patient with idiopathic CD4+ T-lymphocytopenia was also reported." (PMID 31752146, 2019). "In general patients with impaired T-cell function especially to a CD4 counts of less than 50/mm3, whether it is inherited or acquired immunocompromised disease or patients under treatment depending on degrees of immune-suppression, are at higher risk of Cryptosporidium and microspora infection." (PMID 30803212, 2019). "Microsporidiasis in HIV infection infection was common amongst patients with with low CD4+ counts, diarrhoea, body rashes and cough." (PMID 29043165, 2013). "Microsporidiosis appears to occur most commonly in severely immunodeficient individuals, especially patients having CD4 + T-lymphocyte counts <100 cells/μL, although it is a rare condition even among these individuals." (PMID 21559864, 2011). "However, intestinal microsporidiosis could be predicted among patients who have < 200 CD4 cells/μl, have poor hand hygiene after contacting soil and before eating, usually eat unwashed raw produce, or do not possess indoor latrines." (PMID 34983416, 2022). "Further, in our study, the incidence of microsporidiosis in HIV-positive group did not significantly increase with declining CD4+ T cell count level." (PMID 29302628, 2017). "In addition, prevalence of microsporidia infection was 15.4% in immunocompromised patients with chronic diarrhea, 4.1% in patients without diarrhea, and 12.9% in patients with CD4 less than 200 cells/μl." (PMID 31110984, 2019).
myeloproliferative disorder (9 papers, 2019 to 2025). A clonal hematopoietic stem cell disorder, characterized by proliferation in the bone marrow of one or more of the myeloid (i.e., granulocytic, erythroid, megakaryocytic, and mast cell) lineages. "Patients with myeloproliferative neoplasms also exhibited a lower frequency of Tregs but a higher frequency of naïve CD4+ T cells, suggesting a delayed or suboptimal immune response." (PMID 40733664, 2025). "In support of this hypothesis, CD4-cre TKO mice develop a similar myeloproliferative disorder that is also rescued in competitive chimeras generated with mixtures of CD4-cre TKO and WT donor BM." (PMID 34343134, 2021). "Furthermore, DCs deficient in antigen presentation (MHCII knockout driven by the CD11c promoter), and consequently the missing collaboration between DCs and CD4+ T cells, led to a myeloproliferative disorder in mice." (PMID 32806517, 2020). "In a small cohort of 13 patients with myeloproliferative neoplasms (MPN), the percentages of naïve and active CD4+ T cells were measured prior, three weeks following, and three months following vaccination." (PMID 35214642, 2022).
ocular sarcoidosis (9 papers, 2011 to 2023). A leading cause of inflammatory eye disease is sarcoidosis. "High CD4/CD8 ratio (higher than 3.5) in the vitreous of patients with ocular sarcoidosis has also been found to be of high diagnostic value with sensitivity and specificity of 100% and 96.3%, respectively." (PMID 24282811, 2013). "In revised IWOS criteria, elevated CD4/CD8 ratio (> 3.5) in bronchoalveolar lavage fluid (BAL) was recognised as one of systemic investigations for diagnosing suspected ocular sarcoidosis." (PMID 37721575, 2023). "In adults, testing CD4/CD8 ratio (> 3.5) in bronchoalveolar lavage fluid (BAL) can be considered in diagnosing suspected ocular sarcoidosis, as stated in revised IWOS criteria." (PMID 37721575, 2023). "Though recent study reported a high CD4/CD8 ratio of lymphocytes obtained from diagnostic vitrectomy using flow cytometric analysis which delivered a high diagnostic value; such evidence provided the diagnosis of presumed ocular sarcoidosis." (PMID 25197595, 2014). "The present results show that an elevated CD4/CD8 ratio and CD4 lymphocyte population represent focal lymphocytosis characteristic of ocular sarcoidosis." (PMID 27930546, 2016). "Intriguingly, the frequency of IL-17RC+ cells among CD3+CD4+ helper T cells, CD14+ monocytes, CD19+ B cells, and CD56+ NK cells was similar between healthy controls and ocular sarcoidosis patients." (PMID 24885153, 2014). "The sensitivity and specificity of CD4/CD8 ratio (> 3.5) in BAL in diagnosing ocular sarcoidosis was not reported in the literature." (PMID 37721575, 2023). "There is no data on the utility of CD4/CD8 ratio (> 3.5) in BAL in ocular sarcoidosis in children or in Blau Syndrome." (PMID 37721575, 2023). "However, it is worth noticing that the CD4/CD8 ratio in the vitreous fluid showed high sensitivity (100%) and specificity (96.3%) for the diagnosis of ocular sarcoidosis in one study." (PMID 37721575, 2023).
Oral ulcer (9 papers, 2009 to 2026). Erosion of the mucous mebrane of the mouth with local excavation of the surface, resulting from the sloughing of inflammatory necrotic tissue. "In oral ulcers, M1 macrophages, M2 macrophages, and CD4 memory-activated T cells represented the top three highest infiltrating fractions." (PMID 35449555, 2022). "In effect, oral ulcers may indicate decreased cluster-differentiated (CD4+) T cell count and increased viral load and thus, may serve as a pointer to the diagnosis, progression, and prognosis of HIV infection." (PMID 37635219, 2023). "In our research, we found that M1 macrophages, M2 macrophages, and CD4 memory-activated T cells were the cell types with the highest degree of infiltration on the wound surface of oral ulcers, which were significantly up-regulated compared to the control group." (PMID 35449555, 2022). "Clinically, mouth ulceration was more prominent in CD4+ and CD8+ T cell-depleted sheep, haemorrhaging and/or oedema of the tongue in mock- and CD4+ T cell-depleted sheep, and depression across CD4+, CD8+, and WC1+ γδ T cell-depleted sheep." (PMID 38357545, 2024).
oropharyngeal cancer (9 papers, 2018 to 2024). Carcinoma, predominantly squamous cell, arising from the epithelial cells of the oropharynx. "Materials and Methods: The abundance of circulating monocyte subsets and peripheral blood CD4/CD8 T cells of oropharyngeal cancer patients and their PD-L1 and PD-1 expression levels were analyzed by flow cytometry." (PMID 35740384, 2022). "Our data revealed different kinds of monocyte subset alterations in patients with oropharyngeal cancer with different immunological consequences in view of monocytic PD-L1 expression and altered percentages of CD4+ effector and CD4+ effector memory T cells." (PMID 35740384, 2022). "High CD4+ and CD8+ TILs were significantly associated with improved OS among oropharyngeal cancers and high CD8+ was associated with improved OS in hypopharyngeal cancers." (PMID 33668519, 2021). "In HPV-positive oropharyngeal cancer (OPC) patients, E6, E7, and L1 capsid proteins were recognized by HPV-specific CD8+ and CD4+ T cells." (PMID 38983849, 2024). "Herein, we report a patient with a Human papilloma virus (HPV)-related oropharyngeal cancer (OPC) and CD4 lymphocytopenia." (PMID 35083153, 2022). "The aim of this study was to investigate the influence of oropharyngeal cancer (OPC) on the abundance of peripheral blood monocyte subsets and immune alterations in CD4/CD8 T cell subsets." (PMID 35740384, 2022). "Interestingly, HPV-positive oropharyngeal cancer demonstrates higher CD4+, higher CD8+, and lower CD4+/CD8+ ratio compared with HPV-negative HNSCC." (PMID 31681613, 2019). "Percentages of PD-1-expressing cells of both CD4 and CD8 T lymphocytes were not significantly altered in oropharyngeal cancer patients compared with healthy donors." (PMID 35740384, 2022).
Respiratory tract infection (9 papers, 2011 to 2023). An infection of the upper or lower respiratory tract. "In contrast, a greater ratio of CD8 to CD4 T cells in the airways is associated with acute lung injury during common respiratory tract infections such as RSV." (PMID 29293660, 2018). "Important predictors of respiratory tract infection in this Brazilian study were found to be viral load and CD4 counts." (PMID 36415339, 2022). "These independent predictors of treatment failure included patients with HIV infection with CD4 < 200 cells/mm3, MDR pathogen, or respiratory tract infection." (PMID 36137077, 2022). "We also showed that the counts of CD3+ T cell, CD4+ T cell, and CD8+ T cell in infected patients were significantly lower than in controls, especially in patients with both bloodstream and respiratory tract infections." (PMID 36443747, 2022). "Another child’s regimen was changed to NVP plus lopinavir/ritonavir, to our surprise, the CD4 cell count rebounded from 10/μl to 750/μl, and VL was below the LOQ after six months despite frequent respiratory tract infections." (PMID 24994004, 2014). "The nCD64 indexes were significantly higher, as well as the counts of CD3+ T cell, CD4+ T cell, and CD8+ T cell were significantly lower in the Mixed Bloodstream Infection Subgroup, compared to the Respiratory Tract Infection Group and Simple Bloodstream Infection Subgroup (p < 0.05)." (PMID 36443747, 2022). "In this context, we found that sputum AFB negativity was more frequent in co-infected subjects with dyspnea, localized interstitial opacities, an intercurrent bacterial, fungal or parasitic respiratory tract infection, with CD4 >50/mm3, no adenopathies and no cavitation." (PMID 21731675, 2011).
Rotavirus infection (9 papers, 2015 to 2025). Infection with any of the rotaviruses. "In this study, we found that acute rotavirus infection was associated with the induction of circulating memory CD4+ T cell subsets, which then return to baseline levels during convalescence." (PMID 37268634, 2023). "Our findings demonstrate limited induction of anti-viral IFN-γ and/or TNF-α-producing CD4+ T cells in rotavirus-vaccinated Malawian children following the development of laboratory-confirmed rotavirus infection." (PMID 37268634, 2023). "Poor induction of CD4+ T cells during rotavirus infection leads to limited antibody production which results in deficient elimination of the rotavirus infection." (PMID 37268634, 2023). "Higher CD4+ T cell compared with CD8+ T cell frequencies in blood have been found in a study of rotavirus infection of gnotobiotic piglets, and in PEDV infection of conventional piglets." (PMID 36851421, 2023). "Similarly, there were more frequencies of intraepithelial IFN-γ-expressing CD4+ T cells and Granzyme B-expressing CD4+ T cells in small intestines from Trim29IEC-KO suckling mice than those from Trim29fl/fl mice after rotavirus infection for 3 days." (PMID 39396665, 2025). "Similarly, there were more frequencies and cell numbers of intraepithelial Ly6A+CCR9+CD4+ T cells in small intestines from Trim29IEC-KO suckling mice than those from Trim29fl/fl mice after rotavirus infection for 3 days." (PMID 39396665, 2025). "However, circulating cytokine-producing (IFN-γ and/or TNF-α) rotavirus-specific VP6-specific CD4+ T cells were rarely detectable in children with rotavirus infection at both acute and convalescent stages." (PMID 37268634, 2023). "Primary rotavirus infection induces the production of mainly serotype-specific antibodies, but reinfections create a broader immune response including the production of cross-reactive heterotypic antibodies and rotavirus-specific CD4+ T cells." (PMID 37268634, 2023). "We sought to identify the CD4+ T cell subsets induced following rotavirus infection in children." (PMID 37268634, 2023). "Strong CD4+ T cell-mediated immune protection following rotavirus infection has been observed in animal models, but its relevance in humans remains unclear." (PMID 37268634, 2023). "Another study described that CD4+ T cells have an important role in the generation of rotavirus-specific intestinal immunoglobulin A (IgA), which is the principal effector of long-term protection against rotavirus infection, and CD8+ T cells have a role in the timely resolution of primary infection." (PMID 29466421, 2018). "The scarcity of circulating rotavirus VP6-specific CD4+ T cells producing IFN-γ and TNF-α in rotavirus-vaccinated children following rotavirus infection was unexpected." (PMID 37268634, 2023). "The detection of CD4+ or CD8+ T cells in saliva would likely coincide with changes to cytokine profiles and help build the story of rotavirus infection in salivary glands." (PMID 37766270, 2023). "There is an urgent need to also consider the characterization of these atypical T-cell profiles and how they relate to conventional CD4 and CD8 T-cell subsets in relation to observed rotavirus infection or vaccine immunogenicity." (PMID 35336866, 2022). "Five studies reported a lower circulating frequency of CD4+ and CD8+ T-cells in response to acute rotavirus infection." (PMID 35336866, 2022). "Together, these findings indicate that the effector memory CD4+ T cells induced by rotavirus infection are unlikely to represent TNF-α or IFN-γ-producing VP6-specific CD4+ T cells." (PMID 37268634, 2023). "However, the rotavirus infection-induced effector memory CD4+ T cells were not targeted at the highly immunogenic rotavirus VP6 protein, and they did not produce TNF-α or IFN-γ." (PMID 37268634, 2023).
scrub typhus (9 papers, 2012 to 2023). Scrub typhus is a rare dust mite-borne infectious disease caused by the Orientia tsutsugamushi bacterium and characterized clinically by an eruptive fever which is potentially serious. "Further studies, including survival of mice deficient in CD4+ T cells and/or other immune cells, during scrub typhus will determine the protective mechanisms in greater detail." (PMID 28723951, 2017). "Using our optimised WBA, we demonstrate polyfunctional CD4+ memory T cell responses to heat-inactivated whole cell OT antigens in humans with acute scrub typhus." (PMID 36961865, 2023). "Using an optimised OT antigen preparation, we demonstrate the presence of polyfunctional antigen-specific memory CD4+ T cells in the blood of scrub typhus patients." (PMID 36961865, 2023). "The activation of CD4+ T cells in infected mice is consistent with recent study of polyfunctional CD4+ T cells in the whole blood of scrub typhus patients." (PMID 38091346, 2023). "Another interesting finding is the remarkable reduction of CD4+ Treg cells in the peripheral blood of scrub typhus patients." (PMID 22905277, 2012). "Interestingly, a high frequency of IFN-γ secreting CD4+ T cells were detected in the unstimulated samples suggesting that the WBA can capture the presence of activated circulating effector T cells in acute scrub typhus." (PMID 36961865, 2023). "It is known that CD44+ activated T cells may contribute to controlling bacterial growth through production of cytokines (e.g. IFN-γ and TNF-α) and granules (granzyme B), and that decreased CD4+ T cell numbers observed in acute scrub typhus patients is likely due to increased cell apoptosis." (PMID 35479068, 2022). "We next applied the optimised WBA protocol to study polyfunctional CD4+ and CD8+ T cell immune responses to OT in patients with acute scrub typhus using a heat inactivated whole cell antigen OT preparation (HI-WCA-OT)." (PMID 36961865, 2023). "By applying the optimised WBA protocol to a clinical study of scrub typhus we demonstrate that the main source of IFN-γ and TNF upon HI-WCA-OT stimulation of WB are CD4+ T cells." (PMID 36961865, 2023). "Our adoptive transfer experiment provided direct evidence of the contribution of CD8+ T lymphocytes and the mixture of the non-CD8 immune cells including potentially CD4+ T cells, macrophages, NK cells, NKT cells, and neutrophils in immunity to scrub typhus." (PMID 28723951, 2017). "In this study, we demonstrate for the first time a significant elevation of ScaA- and TSA56-specific CD4 and CD8 T cells secreting IFN-γ in scrub typhus patients within 2 weeks after recovery." (PMID 29259327, 2017). "Of note, even unstimulated CD4+ and CD8+ T cells showed increased expression of single effector cytokines (IFN-γ and TNF) reflecting the presence of activated effector T cells in peripheral blood of acute scrub typhus patients." (PMID 36961865, 2023). "We also observed increased polyfunctionality in T cells when compared to unstimulated controls and this consisted of the triple (IFN-γ+TNF+IL-2) and double (IFN-γ+TNF) positive CD4+ T cell but not CD8+ T cells during acute infection of patients with scrub typhus." (PMID 36961865, 2023). "Therefore, induction of CD4+ and CD8+ T cells specific to the conserved epitopes might be required to enhance vaccine efficacy for scrub typhus." (PMID 31237478, 2019). "Increased IFN-γ responses are strongly associated with lower levels of bacteremia in a non-human primate model of scrub typhus and a longitudinal study in humans revealed elevated IFN-γ secretion by CD4+ and CD8+ T cells during acute infection." (PMID 36961865, 2023).